RNU6-540P (RNA, U6 small nuclear 540, pseudogene)
Gene: Small nuclear RNA gene on chromosome 5 (65,604,661 to 65,604,761, reverse strand). Ensembl gene ENSG00000207352.
Homologues: Orthologues: chimpanzee U6 (100% identical), mouse Gm22509 (93% identical), dog U6 (90% identical), mouse Gm24927 (90% identical), pig U6 (87% identical), rabbit U6 (79% identical). Paralogues in human: RNU6-19P (94% identical), RNU6-12P (93% identical), RNU6-13P (93% identical), RNU6-21P (93% identical), RNU6-31P (93% identical), RNU6-32P (93% identical), RNU6-1 (92% identical), RNU6-1060P (92% identical), RNU6-140P (92% identical), RNU6-15P (92% identical), RNU6-17P (92% identical), RNU6-18P (92% identical), and 1286 more.